AR (androgen receptor)
Diseases named in the same sentence as AR in open-access papers (continued):
Sharing a sentence is not in itself a finding about the gene and the disease.
prostate carcinoma (continued). "Androgen receptor (AR) is a critical therapeutic target in prostate cancer (PCa), and androgen blockade is known to act synergistically with radiation therapy." (PMID 41573861, 2025). "Enzalutamide, an androgen receptor inhibitor, exhibits a favorable pro-apoptotic effect in diseases such as prostate cancer." (PMID 40356960, 2025). "Particularly intriguing are preclinical prostate cancer models where CDK7 inhibition with the newly identified inhibitor THZ1 attenuates AR signaling and eradicates hormone-sensitive and enzalutamide refractory prostate cancer cells." (PMID 40075623, 2025). "HIC1 inhibits AR expression to suppress the development of castration‐resistant prostate cancer through the IRS2/PI3K/AKT axis." (PMID 41050263, 2025). "The growth of prostate cancer cells depends on androgens, which exert their biological functions through the AR signaling pathway." (PMID 40224223, 2025). "Our results indicate that NKX3.1 is a critical co-factor for AR in prostate cancer cells, and knockdown leads to decreased cell survival, while overexpression is enough to promote growth in androgen depleted and AR-inhibited conditions." (PMID 39858088, 2025). "The androgen receptor (AR) signalling pathway is the principal driver of prostate cancer (PCa) development." (PMID 41028981, 2025). "Another critical factor in the metabolic reprogramming of prostate cancer cells is androgen receptor (AR) signaling." (PMID 40563466, 2025). "Members of the Rho GTPase family are involved in AR signaling pathways that promote prostate cancer cell migration, invasion, and metastasis." (PMID 41301045, 2025). "In prostate cancer, IL-6 from cancer cells activates AR signaling through STAT3, while CAFs produce growth factors (IGF, FGF, and TGF-β) that sustain AR activity." (PMID 41584838, 2025). "CBPD-409 also exhibited superior cytotoxicity when compared with other published p300/CBP degraders, bromodomain inhibitors or HAT domain inhibitors in AR-positive prostate cancer cell lines." (PMID 41044247, 2025). "Here, we report that drugs targeting the androgen receptor (AR) in prostate cancer induce a functional switch of circadian regulator/nuclear receptor REV-ERBα to act as a master regulator in the initial induction of a network of LP driving factors." (PMID 41231955, 2025). "A 2019 study by Spratt and colleagues analyzed genome-wide expression profiles of treatment-naïve primary prostate cancer tissue samples and identified a low AR-active subclass in about 10% of tumors." (PMID 39859392, 2025). "Prostate cancer cells adapt to chronic low testosterone levels by increasing androgen receptor activity, resulting in a 30- to 90-fold rise in androgen receptor levels." (PMID 41257103, 2025). "Targeting the HSF1 pathway with the inhibitor NXP800 decreases HSP72 expression, activates the unfolded protein response, and inhibits AR- and E2F-mediated activity, inhibiting the growth of treatment-resistant prostate cancer models." (PMID 39787247, 2025). "Impressively, assessment of the cytotoxicity of CBPD-409 in a large panel of 136 cell lines from 20 distinct lineages found AR-positive prostate cancer cells to be among the most sensitive models." (PMID 41044247, 2025). "Binding of these ligands to AR promotes receptor stabilization, nuclear translocation, and transcription of androgen-responsive genes that drive prostate-cancer cell proliferation and survival." (PMID 41375042, 2025). "These factors are essential, as Cyclin D1 is pivotal for cell cycle regulation, while Bcl-2 plays a crucial role in promoting cell survival, thus highlighting the importance of aberrant AR signaling in the pathology of prostate cancer." (PMID 40008000, 2025). "Using two prostate cancer cell lines which displayed differential sensitivity to the taxane, Komura and colleagues showed that AR signaling significantly affects the sensitivity of prostate cancer cells to docetaxel." (PMID 39651632, 2025).
prostate carcinoma (continued). "We have previously demonstrated that some A‐ring‐substituted and heterocycle‐fused derivatives of DHT acted as potent AR antagonists, selectively blocking AR transcription programme in prostate cancer cells, including castration‐resistant models." (PMID 40702793, 2025). "While this review provides valuable insights into the mechanisms of YAP and AR in prostate cancer, several critical issues within the current research on prostate cancer remain unaddressed." (PMID 39963114, 2025). "Prostate cancer cells can develop resistance to androgen-targeting therapies through a phenotypic transition from AR-dependent epithelial cells to AR-independent basal-like cells." (PMID 39976818, 2025). "A significant body of research suggests that the androgen receptor (AR) plays a vital role in the development of prostate cancer." (PMID 41050263, 2025). "Prostate cancer (PCa) frequently metastasizes to bone, and PCa cells often employ androgen receptor (AR) AS to evade androgen deprivation therapy or AR signaling inhibitors." (PMID 41268214, 2025). "In response to more potent ATTs, the prostate cancer cells adapt to escape reliance on AR with low AR activity." (PMID 40511682, 2025). "Recently, 3 transcriptional subtypes of human prostate cancer were reported: (i) androgen receptor pathway-positive prostate cancer (ARPC), (ii) mesenchymal and stem-like prostate cancer (MSPC) and (iii) neuroendocrine prostate cancer (NEPC)." (PMID 39865080, 2025). "Exploiting the dependence of SPOP-mutant prostate cancer cells on dysregulated AR signaling represents a promising therapeutic strategy." (PMID 40432836, 2025). "Our findings explore the interactions between potential active components of C. alatavicus and prostate cancer-related targets and offer additional potential chemical probes for AR-driven prostate phenotype pathway modulation." (PMID 40331986, 2025). "Alterations in the AR are prevalent in mCRPC but rarely appear in primary, treatment-naïve prostate cancer." (PMID 40432836, 2025). "Antagonists that are competitive, like enzalutamide, were the first‐line treatments for prostate cancer by preventing the transcriptional action of the androgen receptor (Sanford 2013; Watson, Arora, and Sawyers 2015)." (PMID 39898116, 2025). "To determine if CMV influences cancer‐promoting features such as cell viability, cell proliferation or AR signaling, we turned to prostate cancer models." (PMID 40493023, 2025). "Betulinic acid, a pentacyclic triterpenoid isolated from species such as white birch (Betula pubescens) and the ber tree (Ziziphus mauritiana), exerts anti-prostate cancer effects primarily through AR degradation." (PMID 41020902, 2025). "Although PC-3 and DU-145 cell lines reportedly express AR mRNA and protein, conflicting studies suggest their absence in some contexts, highlighting the complex and heterogeneous nature of AR signaling in prostate cancer." (PMID 41038711, 2025). "This is particularly relevant in androgen-responsive cancers, such as prostate cancer and the luminal androgen receptor (LAR) subtype of triple-negative breast cancer (TNBC)." (PMID 41155247, 2025). "Using network pharmacology, this study revealed that five core bioactive components of C. alatavicus (e.g., Capillarisin) target androgen receptor (AR)/PI3K-Akt pathways in prostate cancer." (PMID 40331986, 2025). "AR activity is commonly hijacked by tumor cells to support growth, underscoring the relevance of targeting this receptor in prostate cancer." (PMID 40952912, 2025). "LNCaP originates from a lymph node metastasis of prostate cancer and retains an aneuploid state, exhibiting abnormal chromosomal counts that confer high androgen sensitivity and robust AR expression." (PMID 41465187, 2025). "EGCG suppresses AR signaling by blocking nuclear translocation and reducing AR protein levels in prostate cancer xenografts through sequestration of AR in the cytoplasm." (PMID 41020902, 2025).
prostate carcinoma (continued). "In sharp contrast to LE-1 and LE-2, LE-3 cells were specifically marked by DPP4 (Dipeptidyl peptidase 4), an AR-stimulated tumor suppressor in prostate cancer." (PMID 41468516, 2025). "These clinical findings align with our cell line data, demonstrating that hypoxia and HIF1α activation promote prostate cancer progression by suppressing AR targets while activating hypoxia-inducible pathways." (PMID 40643528, 2025). "While LKB1 deletion alone led to prostate cancer with a low incidence, the resulting cancerous regions displayed an AR-low phenotype, characterized by the downregulation of AR." (PMID 39743630, 2025). "In mCRPC, a lethal variant of NE prostate cancer, OC2 drives the transition from androgen receptor (AR)-dependent, hormone sensitive prostate cancer to AR-indifferent mCRPC by activating a neural differentiation program." (PMID 40500731, 2025). "Sulforaphane, a sulfur-rich compound abundant in cruciferous vegetables such as broccoli and cabbage, has shown potential in both the prevention and treatment of prostate cancer through modulating AR transcriptional signaling." (PMID 41020902, 2025). "The results demonstrated that PLGA-CUR NPs effectively inhibited prostate cancer cell proliferation through lysosomal activity, apoptosis, inhibition of androgen receptor (AR), and nuclear β-catenin activity." (PMID 40143065, 2025). "With the in-depth research on prostate cancer, the unequivocal central role of AR in this disease has been underscored, while the significant role of the Hippo-YAP pathway has also gained considerable attention." (PMID 39963114, 2025). "Several pivotal randomized controlled trials (RCTs) have established the role of Androgen receptor pathway inhibitors in different stages of prostate cancer." (PMID 41092154, 2025). "This study identified potential diagnostic markers and therapeutic targets by clarifying the effects of these lncRNAs on AR signaling, a key driver of prostate cancer development, which holds significant clinical significance." (PMID 40503765, 2025). "The selective effects of PHD1 depletion on both FOXA1 protein levels and KLK3 transcription underscore its unique and functionally relevant role in modulating androgen receptor signaling pathways in prostate cancer." (PMID 40643528, 2025). "In AR-positive LNCaP prostate cancer cells, 5α-dihydrotestosterone (DHT) significantly increased the expression levels of ASCT2 and glutaminase (GLS), the enzyme responsible for the deamination of glutaminase to glutamate." (PMID 40489535, 2025). "In prostate cancer cells, androgens trigger the binding of AR to Src, this interaction activates Src/Ras/Erk pathway and affects G1 to S cell cycle progression." (PMID 39917165, 2025). "Recent advancements in the management of biochemical recurrence (BCR) following local treatment for prostate cancer (PCa), including the use of androgen receptor signaling inhibitors (ARSIs), have broadened the spectrum of therapeutic options." (PMID 39266730, 2025). "The androgen receptor (AR) is a ligand-activated transcription factor that is a major driver of lethal prostate cancer (CaP) progression." (PMID 40968254, 2025). "The serine and threonine–protein phosphatase 1 regulates key cellular processes and enhances androgen receptor activity in prostate cancer, even under castration-resistant conditions, suggesting a role in disease progression." (PMID 41092058, 2025). "Having identified the global DNA hypomethylation in AR-independent prostate cancer, we proceeded to investigate the therapeutic potential of counteracting this epigenetic alteration." (PMID 39743630, 2025). "TAK1 has been shown to decrease in high-grade human prostate cancer, and TAK1 deficiency promotes prostate tumorigenesis by increasing androgen receptor (AR) protein levels and activity or by activating the p38 MAPK pathway." (PMID 40266671, 2025).
prostate carcinoma (continued). "Prostate cancer cells can adapt to low androgen environments by increasing AR levels, which leads to resistance." (PMID 41079787, 2025). "One of the primary therapeutic targets for prostate cancer has been identified as inhibiting the androgen receptor (AR), which plays a major role in the development of prostate cancer." (PMID 40661813, 2025). "Currently, the most commonway to target prostate cancer cells chemically is to block theandrogen receptor, AR." (PMID 41164275, 2025). "As discussed, an active area of prostate cancer research is to determine the bypass mechanisms of androgen receptor signaling that inevitably arise when therapeutically targeted." (PMID 40840524, 2025). "Typically, the alterations of the AR gene in castration-sensitive prostate cancer were less dominant than in the resistant stage." (PMID 41463218, 2025). "Although, not investigated in BPH, guggulsterones, the active principles of Commiphora wightii have demonstrated to promote apoptosis in prostate cancer cells and have been additionally reported to reduce the expression of androgen receptor." (PMID 41473249, 2025). "The vast majority of localized and metastatic prostate carcinomas depend on androgenic hormones and signaling through the androgen receptor (AR) to maintain survival and growth, a feature that has served as a therapeutic focal point for more than 70 years." (PMID 40956611, 2025). "In line with the genetic approaches, treatment with CBPD-409 resulted in stronger cytotoxicity in all tested AR-positive prostate cancer cell lines relative to GNE-049." (PMID 41044247, 2025). "The loss of canonical prostate cancer markers (AMACR, AR, NKX3.1, and PSA) between biopsy and cell line establishment reflects the cellular evolution commonly observed in treatment-resistant disease." (PMID 41038711, 2025). "Prostate cancer is particularly dependent on the androgen receptor (AR), a transcription factor that regulates several biological pathways essential for the growth and survival of prostate cancer cells." (PMID 40331986, 2025). "By suppressing androgen receptor (AR) signaling, β‐arrestin 2 in prostate cancer prevents cell viability and proliferation." (PMID 40969301, 2025). "Darolutamide is specifically used in prostate cancer to block AR activity and reduce tumor proliferation, especially in cancers that retain sensitivity to androgens." (PMID 40596459, 2025). "Despite achieving low androgen levels, some prostate cancers continue to grow due to persistent AR signaling." (PMID 41235005, 2025). "We evaluated their uptake, impact on prostate cancer cell viability, and modulation of androgen receptor and prostate-specific antigen (PSA) expression." (PMID 41092058, 2025). "Isoflavones can block the androgen receptor (AR), a protein that is required for the growth and dissemination of prostate cancer." (PMID 40078339, 2025). "Despite radical prostatectomy and radiotherapy, there are numerous candidate drugs available for the management of prostate cancer by targeting the androgen receptor, DNA damage repair, and other pathways." (PMID 40420092, 2025). "Mainly, AGR3 potentially acts as a negative regulator of AR, inhibiting the activation of genes crucial for controlling prostate cancer growth." (PMID 40265030, 2025). "To determine those proteins (including HSPs) that bind both AR and AR-V7, we conducted FLAG-tagged immunoprecipitation–mass spectrometry (IP-MS) on AR-negative PC3 prostate cancer cells overexpressing FLAG-tagged AR-FL and AR-V7 proteins." (PMID 39787247, 2025). "ARV-110 selectively degrades the androgen receptor (AR), which is a critical driver of prostate cancer progression." (PMID 40574056, 2025). "The genome-wide distribution profiles of H2BK5ac and H2BK20ac in prostate cancer cells confirmed a specific enrichment of H2BNTac at AR/p300 co-bound enhancers." (PMID 41044247, 2025).
prostate carcinoma (continued). "In summary, these findings show that CMV promotes proliferation and androgen signaling in AR‐expressing prostate cancer cells." (PMID 40493023, 2025). "Rigorous phenotypic characterization of mCRPC tumors and PDX models has further reinforced the importance of AR and neuroendocrine features in classifying advanced prostate cancer." (PMID 40840524, 2025). "The androgen receptor (AR) remains the main oncogenic driver and a major therapeutic target for advanced prostate cancer." (PMID 39787247, 2025). "Firstly, androgen receptor (AR) signaling is fundamentally involved in both the onset and advancement of prostate cancer, as most prostate cancers rely on the activation of the AR pathway to sustain cellular survival and proliferation." (PMID 41514554, 2025). "The increased use of potent androgen receptor antagonists has resulted in a rise in advanced prostate cancers resistant to androgen deprivation therapy with few treatment options." (PMID 40427140, 2025). "Non-coding RNAs regulate the activity of the AR signaling pathway through various mechanisms, influencing the onset and progression of prostate cancer." (PMID 40008000, 2025). "Most prostate cancer patients with distal metastasis receive androgen deprivation therapy followed by anti-AR treatment once the tumor relapses at the castration-resistant stage (CRPC)." (PMID 40094020, 2025). "In summary, in-depth research into the regulatory mechanisms of AR and metabolic reprogramming will bring new hope for the treatment of prostate cancer." (PMID 40008000, 2025). "Studies have demonstrated that AHR functions as an E3 ubiquitin ligase, mediating the ubiquitination and degradation of AR in prostate cancer." (PMID 40771930, 2025). "This study provides a novel mechanism by which prostate cancers undermine drug efficacy through the downregulation of SLC22A3 by FOXA1 competition with AR to bind to SNP rs9364554." (PMID 39858458, 2025). "Prostate cancer (PCa) is the most frequently diagnosed malignancy in men worldwide, with androgen receptor (AR) signaling acting as a central driver of tumor growth and survival." (PMID 41395253, 2025). "Based on integrative deep whole-genome analysis, a study found that most patients with metastatic castration-resistant prostate cancer have an intergenic enhancer region amplification 624 kb upstream of AR, which correlates with increased AR expression." (PMID 40032852, 2025). "Mutant SPOP fails to effectively ubiquitinate AR, resulting in increased AR protein stability and enhanced transcriptional activity, contributing to prostate cancer progression." (PMID 40432836, 2025). "Here, we evaluate CDKI-73’s activity in prostate cancer and demonstrate that it promotes apoptosis and inhibits signaling by AR, MYC, and BRD4." (PMID 39117800, 2024). "Previously, we identified DUSP22 as a negative regulator of the EGFR-androgen receptor (AR) signaling pathway in prostate cancer cells through dephosphorylation." (PMID 38877005, 2024). "Proxalutamide is a novel androgen receptor inhibitor currently used in the castration-resistant prostate cancer patients, and it has entered Phase III clinical trials." (PMID 39166104, 2024). "In particular, the growth and survival of prostate cancer cells is initially dependent on androgen receptor signaling." (PMID 38673756, 2024). "A similar effect was seen in AR-expressing prostate cancer patient-derived xenograft model (TM00298)." (PMID 39144725, 2024). "The potential of these androgen receptor degraders to treat castration-resistant prostate cancer is substantiated by the advancement of six PROTACs and two monomeric androgen receptor degraders into phase I or II clinical trials." (PMID 38339414, 2024). "SRC-1 has the second-most potent effect in prostate cancer, as the prostate is rich in endogenous androgen, which regulates various physiological activities through the androgen receptor (AR), and SRC-1 is a crucial mediated of these effects." (PMID 38553750, 2024).